CRP (C-reactive protein)
Diseases named in the same sentence as CRP in open-access papers (continued):
Sharing a sentence is not in itself a finding about the gene and the disease.
Stroke (continued). "Recently, Evans and colleagues conducted a study to explore the association between CRP levels and stroke in 30,239 Afro-American and Caucasian individuals." (PMID 37760885, 2023). "Firstly, innate immunity markers including neutrophils, NLR, SII and CRP exhibited significant correlations with risk of various brain disorders, including dementia, PD, stroke, MDD, and anxiety." (PMID 38071240, 2023). "Among AF patients, CRP was positively correlated with stroke risk and related to stroke risk factors and prognosis (mortality and vascular events)." (PMID 36902819, 2023). "In conclusion, CRP levels in the first 24 h of ischemic stroke are associated with cardiac complications or death within 30 days after stroke." (PMID 37119383, 2023). "Though little is known about its direct role in SVD, there is an established connection between CRP and cardiovascular-event risk, including stroke." (PMID 37685924, 2023). "This study further corroborates the differential predictive value of CRP in stroke risk assessment among individuals with different ethnic backgrounds, similar to that found in CAD." (PMID 37760885, 2023). "Subpopulations characterized by the inflammation indicators hs-CRP and IL-6 showed high risk of stroke recurrence, poor functional outcome, and mortality." (PMID 37248226, 2023). "While there is some evidence for the role of SEP for predicting stroke, CRP has a well-established link with stroke." (PMID 37808231, 2023). "There appears to be a dose response with this early risk, as evident by increasing risk of stroke–heart syndrome and death from CRP 1–3 mg/L to CRP > 3 mg/L." (PMID 37119383, 2023). "A retrospective review showed that 26 studies reported an association of CRP with recurrent stroke, of which 12 (46%) described a positive association, a result that is consistent with what we obtained." (PMID 37051146, 2023). "Only one real-world study found that with LDL-C ≥ 1.42 mmol/L in patients with ischemic stroke, hs-CRP ≥ 2 mg/L was associated with a higher risk of stroke recurrence." (PMID 37095492, 2023). "No significant increased risk of Takotsubo cardiomyopathy was found in patients with CRP levels > 3 mg/L within the first 24 h of stroke compared to those with CRP levels < 1 mg/L (HR 1.09, 95% CI 0.63–1.90)." (PMID 37119383, 2023). "Logistic regression analysis showed that right hemisphere, homocysteine (HCY), C-reactive protein (CRP), and stroke severity (SS) were independent risk factors for the development of stroke recurrence in AIS patients." (PMID 37051146, 2023). "For example, elevated CRP is associated with impaired functional outcomes and increased mortality due to stroke." (PMID 36675440, 2023). "Although post-stroke CRP levels have been previously associated with long-term outcomes, CRP levels and the relationship with early cardiac complications (i.e., SHS) have not been previously investigated." (PMID 37119383, 2023). "Concerning thrombotic events, CRP was positively correlated with the risk of stroke, related to risk factors and prognosis, and associated with the risk of AF recurrence." (PMID 38203704, 2023). "Higher levels of IL-6 and CRP have been associated with skeletal muscle loss, whereas changes in molecular biomarkers, such as CRP in the blood, urine, and other body fluids, have been associated with post-stroke cognitive decline." (PMID 37373767, 2023). "High CRP levels, as in many other disorders, are associated with poor prognosis and mortality in stroke patients." (PMID 37577267, 2023). "Zacho and colleagues conducted a comprehensive investigation on the potential causal association between CRP levels, ischemic cardiopathy, and stroke." (PMID 37760885, 2023). "In particular, in-hospital stroke and elevated C-reactive protein were associated with increased mortality." (PMID 37034098, 2023).
Stroke (continued). "It is necessary to monitor the age, NIHSS score, nasogastric tube feeding status, and CRP level of stroke patients and identify high-risk groups using the developed nomogram to provide active nursing interventions to prevent SAP." (PMID 38063586, 2023). "Among a cohort of stroke patients, post-stroke apathy at six months was significantly associated with elevated C-Reactive Protein (CRP) concentrations." (PMID 36572691, 2022). "Cell death, brain injury, and blood-brain barrier disruption have been associated with elevated concentrations of CRP post-stroke." (PMID 36699006, 2022). "In human stroke victims, gut dysbiosis was shown to be associated with serum inflammatory markers, interleukin-6, C-reactive protein, and white blood cell counts." (PMID 35052672, 2022). "Stroke has been reported to be associated with the presence of systemic inflammation and increased inflammatory biomarkers in the blood, and plasma CRP level has been linked with the risk of stroke in patients with AF." (PMID 35492601, 2022). "In other neurological diseases, in which the proportion of inflammation is presumed, for example in stroke, CRP is increased, and it has been associated with an unfavorable outcome." (PMID 35677334, 2022). "An increase in the inflammatory marker CRP has repeatedly been observed in both dysphagia and stroke and is associated with poor clinical outcome." (PMID 36703642, 2022). "Many patients with stroke with increased levels of CRP have a greater risk of death within 72 hours of stroke event in comparison to patients having normal CRP levels." (PMID 36381804, 2022). "On the other hand, CRP and fibrinogen have been reported to be associated with an enhanced risk of stroke and coronary events in apparently healthy individuals." (PMID 36119741, 2022). "In a cohort study, 96 stroke patients who experienced vascular events associated with proinflammatory coagulopathy were found to have high CRP, D-dimer and ferritin levels." (PMID 35476075, 2022). "The authors stated that the relationship between CRP concentrations and risk of stroke was linear and that the high values of this relationship can be treated as an independent risk factor for stroke." (PMID 35330458, 2022). "CRP concentrations again have been associated with poor functional outcomes, increased mortality, and increased susceptibility to infection post-stroke." (PMID 38566903, 2022). "Further, increased disease activity is also linked to higher risk of myocardial infarction, stroke, and cardiovascular-related death, with elevated CRP levels acting as a surrogate for disease activity." (PMID 36333367, 2022). "Enzyme-linked immunosorbent assays (ELISA) implicated that the hs-CRP level was higher in the subsequent stroke-positive group (p < 0.05)." (PMID 36278219, 2022). "The Hs-CRP test measures even low levels of inflammation and indicates the risk of cardiac disease and stroke." (PMID 36381804, 2022). "Few studies have investigated the association between the CRP gene and patients’ stroke subtypes and patient-based characteristics, which has to be confirmed in more populations." (PMID 36448063, 2022). "We also found direct associations of all 5 markers with myocardial infarction (MI) risk, and of GDF-15, NT-proBNP, CRP and cystatin-C with stroke risk." (PMID 34935094, 2022). "Their activation and recruitment at the site of infarction always coincide with the maximum synthesis of proinflammatory mediators (such as TNF-α and IL-6) and associated biomarkers (such as CRP), which result in neuronal damage after stroke." (PMID 35978885, 2022). "Second, information on white blood cell count, high sensitivity C-reactive protein, and data of other inflammatory biomarkers and biochemistry data were also not available in the claimed database to assess the association with stroke." (PMID 33536376, 2021).
Stroke (continued). "For this particular RA population, our findings underscored the contribution of systemic inflammation to stroke development in RA patients, with CRP and ESR inflammatory factors as independent risk factors for stroke in RA patients, also confirmed previously." (PMID 34081620, 2021). "In an apparent healthy population, hs-CRP had already been found to be related with increased risk of myocardial infarction and stroke." (PMID 34753497, 2021). "Particularly, history of venous thromboembolism, low hemoglobin, altered platelet count and elevated CRP were associated with cancer in stroke patients, as well as higher in-hospital mortality and inferior post-stroke survival." (PMID 33945004, 2021). "Elevated CRP levels have been shown to be an independent risk factor for diseases such as myocardial infarction, peripheral vascular disease, and stroke." (PMID 34332541, 2021). "Increasing CRP quartiles exhibited significant associations across many cardiovascular risk factors and comorbidities, apart from hyperlipidemia and previous stroke." (PMID 34032303, 2021). "The serum C-reactive protein is a marker of systemic inflammation and has been associated with an increased risk of stroke and carotid atherosclerotic plaque instability." (PMID 34441429, 2021). "A key marker used to study this clinically is serum levels of CRP, with a history of stroke associated with increased concentrations of serum CRP." (PMID 34884906, 2021). "As expected, in addition to the CHA2DS2-VASc score components, the LDL, CRP, and endocan levels were higher for the patients at high risk of stroke while their white blood cell was statistically significantly lower." (PMID 33443627, 2021). "In multivariate logistic model, after correcting conventional risk factors and TOAST subtype, both CRP and IL‐6 level were independent predictors for mortality, stroke severity, and mRS‐defined outcome." (PMID 33314753, 2021). "The elevated plasma level of acute phase reactant C-reactive protein (CRP) has been reported to be associated with a higher risk of stroke." (PMID 35126096, 2021). "In the GUSTO study, the results of multivariate analysis concluded that, compared with other risk factors such as stroke, heart failure, elevated C-reactive protein, and ST-segment changes, CKD is more related to death and myocardial infarction." (PMID 34211566, 2021). "In support of this, serum CRP levels are associated with poor cognition and functional outcome in the acute phase post-stroke." (PMID 34884906, 2021). "Several studies have found an association between CRP concentrations and cardiovascular events such as acute myocardial infarction, stroke, and the progression of peripheral arterial occlusive disease." (PMID 34204618, 2021). "Additional inflammatory markers (including CRP) have been associated with poor outcome after stroke and greater disability." (PMID 31037709, 2021). "Studies suggested that depressive symptoms are positively associated with inflammatory factors (i.e., C-reactive protein, IL-6, and Tumor necrosis factor alpha), which are related to stroke." (PMID 34706692, 2021). "We have previously reported that elevated ESR, LDL levels, and CRP levels ≥230 mg/L were independent risk factors for RA patients in developing stroke." (PMID 34081620, 2021). "We examined the association of NLR with CRP and D-dimer levels among cancer patients because CRP and D-dimer have been reported to have relationship with cancer-associated stroke." (PMID 33928250, 2021). "In our previous studies, an increase in WBC counts and CRP levels was associated with a worse course in the acute phase of stroke and post-stroke functional status." (PMID 34768603, 2021). "A recent review highlighted that changes in molecular biomarkers such as C-reactive protein (CRP), interleukin 6 (IL-6) and IL-10 in blood, urine, and other body fluids are associated with post-stroke cognitive decline." (PMID 33671531, 2021).
Stroke (continued). "Cox proportional hazard models were used to evaluate the risk of hs-CRP on cardiovascular events (composite of myocardial infarction, stroke and vascular mortality) and all-cause mortality." (PMID 34753497, 2021). "The clinical features of stroke patients with cancer (cancer-associated stroke) are multiple vascular lesions, cryptogenic stroke, and increased D-dimer and C-reactive protein (CRP) levels." (PMID 33928250, 2021). "Regarding inflammation, elevated levels of C-reactive protein (CRP) are present among patients at risk for first-ever myocardial infarction and stroke." (PMID 34305782, 2021). "The multivariable model included demographic characteristics, clinical findings at admission, vascular risk factors, NIHSS at admission, stroke subtype, acute stroke treatment, and serum levels of CRP, FSG, and galectin-3." (PMID 33686023, 2021). "CRP, a controversial independent risk factor for stroke and an underlying acute inflammatory risk factor, has been reported to be a predictor of stroke and ischaemic stroke." (PMID 34856939, 2021). "Several laboratory parameters were linked with cancer in stroke patients, including elevated D-dimer levels, low hemoglobin, higher levels of C-reactive protein (CRP), and higher erythrocyte sedimentation rate (ESR)." (PMID 33945004, 2021). "Secondary outcomes were all-cause mortality, stroke, urgent coronary revascularization, levels of follow-up high-sensitivity C-reactive protein (hs-CRP), and drug-related adverse events." (PMID 34169101, 2021). "Another study using CRP as an inflammatory marker showed that increased levels of serum CRP were associated with global cognitive impairment among post-stroke survivors." (PMID 34276542, 2021). "CRP, a typical inflammatory marker, can induce other proinflammatory factors and was associated with an increased risk of stroke." (PMID 34030636, 2021). "We found that exhaled decanal tracks CRP and IL-6 levels post-stroke and correlates with several metabolic pathways associated with a post-stroke inflammatory response." (PMID 34753981, 2021). "Healthy men in the highest quartile of hs-CRP levels had a 3 times higher risk of myocardial infarction and a 2 times higher risk of stroke as compared to healthy men in the lowest quartile." (PMID 34753497, 2021). "Associations between CRP and the risk of developing a certain stroke subtype have already been investigated, and elevated CRP levels have been reported in small-vessel disease or posterior circulation infarctions." (PMID 34135849, 2021). "Previously, conventional stroke biomarkers have pinpointed a clear relationship between inflammation and lacunar stroke in which c-reactive protein was found to predict the risk of recurrent stroke." (PMID 34769320, 2021). "Our study revealed that higher levels of CRP are associated with greater depressive symptoms at day 8 after stroke, but their effects on depressive symptoms 3 months after stroke are less significant." (PMID 31996746, 2020). "According to epidemiological studies CRP is an independent risk factor for coronary heart disease, stroke and PAD, and high hsCRP is associated with severe PAD." (PMID 33033455, 2020). "CRP and other inflammatory biomarkers, such as IL-6 and IL-8, are increased after stroke and have been linked to recurrent vascular events." (PMID 32733466, 2020). "We cannot exclude the possibility that our study had too low statistical power to detect an association between CRP and depressive symptoms occurring 3 months after stroke." (PMID 31996746, 2020). "Stroke-associated pneumonia was significantly associated with higher age, dysphagia, greater stroke severity, embolectomy, nasogastric tubes, and higher baseline C-reactive protein (CRP)." (PMID 33240188, 2020). "Over-nutrition as a risk factor for stroke, enhances formation of inflammatory mediators such as c-reactive protein, tumour necrosis factors, intracellular adhesion molecule and interleukin-6." (PMID 33598073, 2020).
Stroke (continued). "Our study aimed to explore the association between circulating CRP and post-stroke depressive symptoms." (PMID 31996746, 2020). "In the univariate analysis, higher CRP was associated with greater depressive symptoms 3 months after stroke." (PMID 31996746, 2020). "Among the plasma biomarkers measured, only hs-CRP was associated with an increased risk of recurrent TIA/stroke (P < 0.05)." (PMID 32733466, 2020). "Our study aimed to explore the association between serum C-reactive protein (CRP) and post-stroke depressive symptoms." (PMID 31996746, 2020). "LAA had a stronger activation of inflammation than CSVD in terms of stroke pathogenesis, which has been reported to be associated with changes in CRP levels." (PMID 33013672, 2020). "There is strong evidence linking circulating TMAO levels to increased risk for myocardial infarction and stroke, even in low risk individuals (e.g., age <65 years, women, low lipid levels, low C-reactive protein (CRP) levels)." (PMID 31940332, 2020). "Serum albumin level, C-reactive protein (CRP), stroke, and age ≥ 70 years were significantly associated with pneumonia defined by CT after adjustment for age." (PMID 33260480, 2020). "Stroke-associated pneumonia patients showed a CRP increase from admission (median 3.2 mg/L) to BL (10.7 mg/L) and 48 h (52.3 mg/L), decreasing again at 120 h (37.2 mg/L)." (PMID 33240188, 2020). "In conclusion, higher levels of CRP are associated with greater depressive symptoms at day 8 after stroke, but their effects on depressive symptoms 3 months after stroke are less significant." (PMID 31996746, 2020). "CRP level measurement should be considered for post-stroke death risk stratification in patients with acute ischemic stroke." (PMID 30718369, 2019). "Studies have shown that post-stroke fatigue is associated with the presence of inflammatory markers C-reactive protein and interferon-α12." (PMID 31273283, 2019). "CRP elevation can increase the risk of recurrent stroke, which was associated with an increased risk of death." (PMID 30718369, 2019). "Older age (≥80 years), moderate stroke, and elevated CRP level were independent risk factors of recurrence at 12 months after SAO, but alcohol drinking was negatively associated with recurrence." (PMID 30808986, 2019). "Patients with initial lower BMI level, a younger age at admission, stroke, and elevated CRP have a high risk of poor outcomes, requiring close c-TA monitoring and more aggressive management." (PMID 30670069, 2019). "Serum vitamin D was inversely associated with the levels of interleukin-6 and C reactive protein, suggesting a potential anti-inflammatory role for vitamin D underlying in stroke." (PMID 31315602, 2019). "Increased blood CRP levels have been shown to be associated with an increased risk of stroke in the general population." (PMID 30720741, 2019). "Associations of CRP levels with risks of total stroke and its subtypes were examined in the Circulatory Risk in Communities Study, prospective nested case-control study of 13,521 Japanese men and women aged 40–85." (PMID 30254628, 2018). "A recent aggregate data meta-analysis considered prospective observational studies that enrolled participants from the general population, measured hs-CRP levels and reported adjusted estimates of stroke risk in at least three CRP categories." (PMID 30254628, 2018). "The AHEI-2010 was inversely associated with stroke (HR 0.66; 95% CI 0.42, 0.88) incidence, aortic pulse wave velocity, and C-reactive protein." (PMID 28293738, 2018). "The impact of CRP on risk of stroke, stroke subtypes, and ischemic heart disease in middle-aged Japanese was further explored in a prospective, population-based Study." (PMID 30254628, 2018). "Increased concentrations of serum CRP have recently been associated with cerebral microstructural disintegration, suggesting an involvement of CRP in silent stroke-associated vascular dementia and, possibly, hemorrhagic stroke." (PMID 30254628, 2018).